EGFR (epidermal growth factor receptor)
Diseases named in the same sentence as EGFR in open-access papers (continued):
Sharing a sentence is not in itself a finding about the gene and the disease.
lung cancer (continued). "For lung cancers, EGFR alterations were frequent alterations; they are actionable with approved drugs (since several EGFR inhibitors are approved, including erlotinib, which is authorized for lung cancer)." (PMID 26848768, 2016). "Next, we explored whether inhibition of MET, the receptor of HGF, could restore the sensitivity to gefitinib in lung cancer cells with wild-type EGFR that were pretreated with HGF." (PMID 26919104, 2016). "Data from lung cancer cell lines suggest that SALL4 downregulation may result in degradation of EGFR and IGF1R proteins, possibly in part through CBL-B." (PMID 27705911, 2016). "Emerging pre-clinical and epidemiologic data suggest that low vitamin D levels may favor the growth of EGFR mutant lung cancer." (PMID 26654942, 2016). "Indeed, we found that TOPK was significantly upregulated and profoundly activated in lung cancer cells that exhibited resistance to EGFR-TKIs." (PMID 26745678, 2016). "In lung cancer patients with wild type EGFR tumors, EGFR inhibition could also be used in the second or third line of treatment with modest and variable clinical responses." (PMID 27248176, 2016). "Our findings imply that EGFR driven lung cancer cell lines may have distinct inflammatory phenotype with a potential to elicit anti-tumor T cell responses." (PMID 27467256, 2016). "In this study, we discovered that compound 5i could not only inhibit the proliferation of A549 and H460 lung cancer cells (EGFR wild type) but also H1975 lung cancer cells (EGFR acquired mutation, L858R and T790M mutation)." (PMID 27786281, 2016). "Our result may provide an insight into the association of mutant EGFR and CDH5 expression in lung cancer and aid further development of target therapy for NSCLC in the future." (PMID 27362942, 2016). "Likewise, IL-8 was reported to induce stemness and EGFR inhibitor resistance in lung cancer, and CXCR1/2 inhibition decreased tumor growth, metastasis, and angiogenesis of lung cancer xenografts." (PMID 27348007, 2016). "IL-8 has also been shown to grant resistance to gefitinib for EGFR-mutant lung cancer cells." (PMID 27348007, 2016). "Until now, there was no direct evidence to prove the relationship between EGFR mutations of lung cancer and PD." (PMID 27801674, 2016). "Large scale sequencing efforts demonstrate that EGFR mutations are most frequently detected among lung cancer patients with adenocarcinoma histology, never-smoker status, East Asian ethnicity, and female sex." (PMID 26654942, 2016). "To analyze the early response of EGFR ctDNA to EGFR-TKI treatments, we conducted a prospective study, wherein the quantitative changes in EGFR ctDNA were evaluated in the first 3 weeks of EGFR-TKI treatment for lung cancer with activating EGFR mutations." (PMID 27708242, 2016). "Late-stage lung cancers observe poor response to chemotherapy and radiotherapy, although tyrosine kinase inhibitors were investigated to be efficient in reducing tumor tissue in NSCLC with epidermal growth factor receptor (EGFR) mutations." (PMID 26985396, 2016). "In contrast, we surmise that pharmacologic doses of vitamin D3 may be required for therapeutic benefit in individuals diagnosed with advanced EGFR mutant lung cancer who receive erlotinib." (PMID 26654942, 2016). "To date, inhibition of EGFR has been the most widely used targeted therapy in lung cancer." (PMID 26760963, 2016). "The treatment with IFNγ up-regulated the surface expression of MHC-I, MHC-II, and PD-L1 more frequently on lung cancer cell lines sensitive to erlotinib than on those resistant erlotinib, suggesting that EGFR-driven lung cancer may be immunologically reactive." (PMID 27467256, 2016).
lung cancer (continued). "For lung cancer patients with MPEC and EGFR gene mutations, intrapericardial BEV might therefore be particularly effective." (PMID 27203219, 2016). "Here, we investigated the effect of EGFR signaling inhibition on skin keratinocytes and various lung cancer cell lines for the expression of MHC-I, MHC-II, and PD-L1, and impact on T cell mediated tumor killing in order to delineate the link between EGFR signaling pathways to anti-tumor immunity." (PMID 27467256, 2016). "In concordance with these observations, our data suggest that EGFR/KRAS driven signaling might activate YAP1 leading to its nuclear translocation in lung cancers." (PMID 26716514, 2016). "Never smoker is more frequent in female lung cancer patients and AD with lepidic growth, which frequently have EGFR mutation, is more popular histology in women." (PMID 27526096, 2016). "Therefore, excessive TOPK expression and activity correlates with resistance to EGFR-TKIs in lung cancer cells." (PMID 26745678, 2016). "Since CDH5 has been reported to be a potential target for cancer therapy, our results may also contribute to the future development of anti-CDH5 therapy in conjunction with EGFR-TKI therapy in lung cancer patients." (PMID 27362942, 2016). "Therefore, we next sought to determine the importance of the PI3K and MAPK downstream signaling pathways in lung cancer cells with mutant or wild-type EGFR using PI3K inhibitors and MEK inhibitors." (PMID 26919104, 2016). "Stable lung cancer cells transfected with wild type and mutant EGFR genes were also established." (PMID 27362942, 2016). "As it is an established practice to treat NSCLC patients with EGFR TKIs and there increasing evidence that FAK plays a major role in lung cancer growth and progression, we set out to test the utility of combining the EGFR inhibitor erlotinib with FAK inhibition in NSCLC." (PMID 26962872, 2016). "Thus, the results from clinical NSCLC samples were consistent with our finding from in vitro experiments that MIIP accelerated EGFR protein turnover and resulted in the inhibition of lung cancer cell proliferation." (PMID 26824318, 2016). "Importantly, we report for the first time on the development of lung cancer in a transgenic mouse model with lung epithelium-specific overexpression of human wt-EGFR and that these tumors are highly sensitive to TKI treatment." (PMID 26646697, 2016). "Since EGFR is overexpressed in various types of epithelial cancers, including pancreatic, colorectal, breast, and lung cancer, it has been suggested that EGFR might be an appropriate target for cancer therapy." (PMID 27833557, 2016). "However, two clinically validated and FDA approved lung cancer predictive biomarkers (EGFR and ALK translocations) occur in only about 20% of lung adenocarcinomas and acquired resistance develops to first generation drugs." (PMID 28018791, 2016). "Collectively, these findings indicate that combined inhibition of GPR171 and EGFR may be a promising strategy for lung cancer treatment, reflecting the fact that GPR171 induces tumorigenesis in an EGFR-independent manner." (PMID 26760963, 2016). "Taken together, we hypothesize that cordycepin can interrupt EGFR signal transduction to inhibit lung cancer cell proliferation and induce apoptosis." (PMID 27689974, 2016). "A significant fraction of lung cancers that develop in never-smokers contain activating mutations in the Epidermal Growth Factor Receptor (EGFR) gene and depend upon EGFR signaling for survival." (PMID 26654942, 2016). "As with previous lung cancer data, the second anti-EGFR biotinylated antibody bPan behaves similarly as bCet in FaDu, suggesting that engagement of EGFR by any AvidinOX-anchored anti-EGFR antibody might lead to the same outcome." (PMID 26575422, 2016).
lung cancer (continued). "The array was comprised of 84 lung cancer cases derived from lifetime-never smokers, where EGFR mutations are prevalent." (PMID 26654942, 2016). "The unique expression pattern of SALL4 in lung cancer suggests that it can potentially be a good drug target for personalized medicine, targeting the lung cancer subtypes that cannot be treated by current targeted therapies like EGFR and ALK inhibitors." (PMID 27705911, 2016). "Our analysis of lung cancer patients within the same generation, the siblings, also revealed no trend of higher similarity in the spectrum of EGFR mutations." (PMID 27449093, 2016). "To fill this knowledge gap, we determined vitamin D receptor (VDR) expression in human lung tumors using a tissue microarray constructed of lung cancer cases from never-smokers (where EGFR gene mutations are prevalent)." (PMID 26654942, 2016). "Here we show that a minor portion (9.8%) of lung cancer patients negative for EGFR mutations responded to TKI treatment." (PMID 26646697, 2016). "Therefore, follow up studies should include combining imetelstat with targeted therapies such as erlotinib in EGFR mutant lung cancer and crizotinib in EML4-ALK fusion lung cancer." (PMID 27192120, 2016). "Therefore, MIIP accelerates degradation of both semiglycosylated and mature EGFR in H1299 lung cancer cells." (PMID 26824318, 2016). "While the EGFR mutation rate was lower in the younger group (52.5% versus 60.6%, P = 0.001), the primary site of lung cancer and stage distribution were not significantly different." (PMID 27191886, 2016). "Notably, the effect of miR-200c or NOTCH1 siRNA was not limited to EGFR-mutated cells, suggesting that miR-200c regulates a universal and conserved NOTCH1-ERBB3 signalling axis in lung cancer cells." (PMID 27456471, 2016). "Intratumoral heterogeneity has been reported in lung cancer having both EGFR and ALK alterations." (PMID 26992209, 2016). "We also checked the efficacy of cetuximab against wt-EGFR driven lung cancer in our mouse model." (PMID 26646697, 2016). "As there were various EGFR mutation subtypes in YAP1 carriers, other second hits may be needed to initiate lung cancer formation." (PMID 27449093, 2016). "Moreover, EGFR inhibitors have a poor efficacy in patients with advanced lung cancer, which accounts for more than half of the lung cancer patients." (PMID 27558312, 2016). "We asked whether this artificial cell line mimicked human lung cancer cell line sensitive to EGFR TKI treatment at EGFR expression level." (PMID 26646697, 2016). "The EGFR mutations showed a close relationship with clinical characteristics of patients with lung cancer and mainly appeared in non-smoking female patients with adenocarcinoma lung cancers." (PMID 27992557, 2016). "The overall response rate (ORR) to TKI in EGFR mutant lung cancers varies between 60 and 90%." (PMID 27032107, 2016). "The inhibitory effect of erlotinib was stronger in lung cancer cell-lines with EGFR mutation than it was in those without the mutation." (PMID 27070423, 2016). "For metastatic colorectal and lung cancer patients, where treatment with anti-EGFR monoclonal antibodies is only effective in patients whose tumours are RAS wild type, sequencing 3 exons of KRAS and 3 exons of NRAS is required, and this will possibly also be the case for other tumour types shortly." (PMID 26919633, 2016). "Additionally, the combination of WZ4002 with trametinib, another MEK inhibitor, prevents the development of acquired resistance in EGFR-mutant lung cancer models." (PMID 28149837, 2016). "Since exon 21 missense mutation is also related to metastasis in lung cancer cells, other metastasis factors may be involved in mutant EGFR gene-related lung cancer metastasis." (PMID 27362942, 2016).
lung cancer (continued). "However, patients with EGFR mutant lung cancer develop disease progression after a median of 10 to 14 months on EGFR TKI." (PMID 26862733, 2016). "TBK1 was described as co-synthetic lethal in KRAS mutant lung cancer but, so far, it has not been associated with EGFR mutant cancer." (PMID 27613601, 2016). "Additionally, the higher expression of EGFR in lung cancer cell lines correlated to the higher level of PD-L1 expression (Pearson’s correlation coefficient r = 0.4851 p<0.0001)." (PMID 27467256, 2016). "Interestingly, EGFR protein expression was not increased by MIIP shRNA in A549 cells, which had the highest endogenous EGFR levels among the lung cancer cell lines we tested." (PMID 26824318, 2016). "A very rare occurring germline T790M mutation predisposes non-smokers to lung cancer, but being a weak oncogene per se it seems to require another EGFR activating mutations to allow tumour development." (PMID 27350784, 2016). "Of note, two of the three confirmed peptides (H9R9 and K9R7) were derived from the well-described shared EGFR-L858R mutation harbored by ∼20% of Asian lung cancer patients, and less frequently (∼5%) by non-Asian patients." (PMID 28123873, 2016). "Our study may help to elucidate the association of EGFR mutations and CDH5 with angiogenesis and metastasis in lung cancer cells." (PMID 27362942, 2016). "Notably, selumetinib in combination with osimertinib did not improve upon the osimertinib/phenformin combination in this model despite the osimertinib/selumetinib combination being very effective in a transgenic model of EGFR-driven lung cancer." (PMID 27861144, 2016). "However, gefitinib is generally effective against EGFR-TKI naïve CNS metastasis in EGFR-mutant lung cancer patients, even though only 1% of gefitinib penetrates into the CNS lesions." (PMID 26716903, 2016). "Thus, tyrosine kinase inhibitors (TKIs) specific for EGFR (EGFR-TKIs) have become a main focus in lung cancer therapy." (PMID 27786281, 2016). "To further confirm our conclusion, we compared cytotoxicity of hyperthermic chemotherapy on EGFR mutation positive cell lines side by side with lung cancer cell lines negative for EGFR mutation." (PMID 26654941, 2016). "Thus, at least in a group of lung cancers with wild-type EGFR, combining EGFR inhibition with the inhibition of other survival dependent signaling pathways might be a better therapeutic strategy, similar to the successful inhibition of lung cancers with EGFR mutations having acquired resistance." (PMID 26919104, 2016). "In addition, mutant EGFR genes potentiates angiogenesis in lung cancer cells, which is inhibited by CDH5 siRNA, and potentiates migration and invasion in lung cancer cells." (PMID 27362942, 2016). "Although univariate analysis suggested a higher EGFR mutation rate among patients with lung cancer family history, the demographics between each group were not even." (PMID 27449093, 2016). "CYP27B1-expressing EGFR mutant lung cancer cells (HCC827) are able to produce 1,25D3 from 25D3." (PMID 26654942, 2016). "Rather than through these canonical signaling pathways that regulate c-Jun, we established here that c-Jun is directly phosphorylated and activated by TOPK in EGFR-TKI-refractory lung cancer cells, leading to the transcriptional activation of AP-1 target genes such as CCND1 and CDC2." (PMID 26745678, 2016). "Molecular testing of EGFR and ALK in lung adenocarcinoma is recommended by the guidelines from College of American Pathologists, the International Association for the Study of Lung Cancer, and the Association for Molecular Pathology." (PMID 26992209, 2016). "The combination of new generation EGFR-TKIs and vorinostat 1 may be a new strategy to overcome the acquired resistance to EGFR-TKIs in T790M mutant lung cancer." (PMID 27752293, 2016). "Wt-EGFR driven lung cancer was hypersensitive to TKI treatment in mouse model." (PMID 26646697, 2016).
lung cancer (continued). "Part of our study involved 40 lung cancer families with at least 2 tumor tissues available within each single family (n = 88) and there was no familial aggregation pattern in EGFR mutation subtypes." (PMID 27449093, 2016). "EGFR signaling is a major pathway of tumorigenesis in lung cancer." (PMID 26760963, 2016). "Nonetheless, these data demonstrate for the first time that human EGFR mutant lung cancers express nuclear VDR protein and may be vulnerable to the anti-cancer activity of vitamin D3." (PMID 26654942, 2016). "We evaluated the role of TOPK in driving EGFR-TKI resistance in xenograft lung cancer mouse models." (PMID 26745678, 2016). "Activation of Hedgehog pathway could mediate EGF receptor tyrosine kinase inhibitor (EGFR-TKI) resistance by inducing EMT in lung cancer cells." (PMID 27455225, 2016). "Accurate and rapid methods to determine the EGFR status are needed for lung carcinoma patients." (PMID 27418143, 2016). "Nevertheless, our study provides novel insights into the mechanism of TKI resistance, and thus suggests that TOPK may be a suitable therapeutic target for overcoming EGFR-TKI resistance in lung carcinomas." (PMID 26745678, 2016). "For KRAS in colon cancer and EGFR in lung cancer previous studies have suggested that cfDNA may be a reasonable alternative to tumour-based genomic testing for determining mutation status." (PMID 26498688, 2015). "In this review, we summarize the emerging role of miRNAs as modulators to regulate the EGFR signaling pathway and mainly focus on miRNAs as predictive biomarkers for anti-EGFR therapy and as novel targets to reverse the resistance of lung cancer cells to EGFR inhibitors." (PMID 26273639, 2015). "In lung cancer, the KRAS and EGFR mutations are exclusive and rarely co-exist in the same patients." (PMID 26126624, 2015). "EGFR is essential for regulating cell proliferation, shedding light on lung cancer treatment." (PMID 26312766, 2015). "However, recent reports to show that HGF can trans-activate EGFR and make the anti-EGFR therapy less effective or indeed make lung cancer resistant to EGFR therapy in lung cancer are very interesting indeed." (PMID 26310485, 2015). "Although an important step in pancreatic cancer, as in EGFR- or ALK-mutant lung cancer or BRAF-mutant melanoma might include investigation of matched targeted monotherapy, many pancreatic tumors likely contain more than one aberration." (PMID 25714017, 2015). "EGFR and KRAS mutations, activation of Src kinase, and elevated expression of interleukin-6 (IL-6) are among several molecular aberrations have been identified in lung cancer that often result in the activation of STAT3." (PMID 26314961, 2015). "The apparently negative association of KRAS and EGFR mutations is not a general phenomenon among known lung cancer proto-oncogenes." (PMID 26047463, 2015). "EGFR-mutant lung cancers are highly sensitive to EGFR-specific tyrosine kinase inhibitors (TKIs)." (PMID 26027747, 2015). "Mutations in the epidermal growth factor receptor (EGFR) gene are more common in lung cancers from never-smokers compared to ever-smokers in both men and women." (PMID 25806093, 2015). "Approximately 1.8 million new lung cancer cases were diagnosed in 2012.1,2 Current recommendations support epidermal growth factor receptor tyrosine kinase inhibitors (EGFR-TKIs) to treat the advanced non-small cell lung cancer (NSCLC) with EGFR-mutation." (PMID 26448029, 2015). "Based on these results, we reviewed the EGFR mutation status of lung cancer specimens, however, we did not have complete EGFR mutation data because our sample set included early records from when EGFR mutation detection was not routine clinical practice." (PMID 26466785, 2015). "Ibrutinib treatment also leads to dose‐dependent inhibition of EGFR phosphorylation and it is speculated that it could be a candidate drug for the treatment of EGFR‐mutant, non‐small cell lung cancer." (PMID 26111359, 2015).